SNAP91 (synaptosome associated protein 91)
Description:
Adaptins are components of the adapter complexes which link clathrin to receptors in coated vesicles. Clathrin-associated protein complexes are believed to interact with the cytoplasmic tails of membrane proteins, leading to their selection and concentration. Binding of AP180 to clathrin triskelia induces their assembly into 60-70 nm coats (By similarity).
Synonyms: KIAA0656; AP180; CALM
Tractability: Antibody: UniProt places it where antibodies can reach, with medium confidence; its Gene Ontology location is reachable by antibodies, with medium confidence. PROTAC: its protein half-life has been measured.
Gene: Protein-coding gene on chromosome 6 (83,552,880 to 83,709,691, reverse strand). Ensembl gene ENSG00000065609.
Subcellular location: Cell membrane; Membrane, coated pit
Subcellular location (Human Protein Atlas): Cytosol; Centriolar satellite
Pathways (Reactome):
Vesicle-mediated transport: Cargo recognition for clathrin-mediated endocytosis; Clathrin-mediated endocytosis
Gene Ontology:
Molecular function: protein binding; 1-phosphatidylinositol binding; clathrin heavy chain binding; phosphatidylinositol-4,5-bisphosphate binding; protein kinase binding; clathrin binding; phospholipid binding
Biological process: regulation of clathrin-dependent endocytosis; vesicle budding from membrane; clathrin coat assembly; clathrin-dependent endocytosis; regulation of receptor-mediated endocytosis
Cellular component: clathrin-coated pit; extrinsic component of presynaptic endocytic zone membrane; synaptic vesicle; clathrin-coated vesicle; membrane; plasma membrane
Genetic constraint (gnomAD): Loss-of-function variants: 13 observed, 49.62 expected, observed/expected ratio (o/e) 0.26, 90% interval 0.17 to 0.42. The upper end of that interval is the gene's LOEUF score, 0.42, which puts it in group 1 of 6, group 1 being the genes least tolerant of losing a copy. Missense variants: 729 observed, 752.34 expected, observed/expected ratio (o/e) 0.97, 90% interval 0.91 to 1.03. Synonymous variants: 297 observed, 279.2 expected, observed/expected ratio (o/e) 1.06, 90% interval 0.97 to 1.17.
Homologues: Orthologues: chimpanzee SNAP91 (99% identical), macaque SNAP91 (99% identical), dog SNAP91 (97% identical), pig SNAP91 (96% identical), guinea pig SNAP91 (95% identical), rabbit SNAP91 (95% identical), mouse Snap91 (93% identical), rat Snap91 (92% identical), tropical clawed frog snap91 (80% identical), zebrafish snap91a (55% identical), zebrafish snap91b (39% identical), Drosophila melanogaster lap (35% identical), and 1 more. Paralogues in human: PICALM (40% identical).
Diseases named in the same sentence as SNAP91 in open-access papers:
SNAP91 is named in the same sentence as 26 diseases in open-access papers, as found by Europe PMC text mining. Sharing a sentence is not in itself a finding about the gene and the disease. The quoted sentences say what the papers report.
schizophrenia (12 papers, 2014 to 2025). A major psychotic disorder characterized by abnormalities in the perception or expression of reality. "In excitatory neurons, synaptic defects are increasingly associated with schizophrenia, and altered expression of SNAP91 has been observed to impact synaptic development." (PMID 39025851, 2024). "SNAP91 is involved in synaptic vesicle endocytosis and recycling, and is considered to be a risk gene in schizophrenia." (PMID 38674386, 2024). "Dysregulation of the genes FURIN, TSNARE1, CNTN4, CLCN3 and SNAP91 have been implicated by eQTL analysis of schizophrenia GWAS hits, which were later separately prioritized by chromatin interaction analysis of schizophrenia risk variants." (PMID 35972862, 2022). "SNAP91 is associated with Alzheimer’s disease, schizophrenia, Parkinson’s disease and colorectal cancer." (PMID 35203526, 2022). "SNAP91 is involved in synaptic function and is a risk gene for the development of schizophrenia." (PMID 40779635, 2025). "Additionally, SNAP91, encoding the synaptosome-associated protein 91, was identified to be a risk gene of schizophrenia." (PMID 36970281, 2023). "SNAP91 was reported as one of the susceptibility genes of schizophrenia." (PMID 33356818, 2021). "Synaptosome associated protein 91 (SNAP91), also known as AP180, has been shown to be significantly increased in schizophrenia compared with normal controls." (PMID 33324198, 2020). "Closer examination of each schizophrenia-associated loci revealed four regions (each encompasses NEK4, FXR1, SNAP91 or APOPT1), where the index SNP in GWAS is in strong linkage disequilibrium with sQTL SNP(s), suggesting dysregulation of AS as the underlying mechanism of the association signal." (PMID 28240266, 2017). "By utilizing the list of sQTL SNPs, we could specify four promising candidate disease susceptibility genes for schizophrenia (that is, NEK4, FXR1, SNAP91 and APOPT1), whose AS are regulated by sQTL SNPs in strong LD with the index SNPs identified in the PGC GWAS." (PMID 28240266, 2017).
Alzheimer disease (4 papers, 2014 to 2025). A progressive, neurodegenerative disease characterized by loss of function and death of nerve cells in several areas of the brain leading to loss of cognitive function such as memory and language. "HSPA9 and SNAP91 are associated with neurodegenerative diseases, including Parkinson’s and Alzheimer’s diseases, emphasizing their roles in physiological aging and age-related disease progression." (PMID 41162879, 2025). "SNAP91 protein level in patients with Alzheimer’s disease was significantly decreased, and the reduction of AP180 resulted in synaptic dysfunction, which might be associated with cognitive deficit." (PMID 33356818, 2021).
glioblastoma (4 papers, 2016 to 2022). The most malignant astrocytic tumor (WHO grade IV). "Kaplan-Meier analysis of SNAP91 in the GSE7696 dataset showed that glioblastoma patients with high expression of SNAP91 exhibited a higher survival ratio compared with those having low levels of SNAP91." (PMID 34211824, 2021).
Parkinson disease (4 papers, 2021 to 2025). A progressive degenerative disorder of the central nervous system characterized by loss of dopamine producing neurons in the substantia nigra and the presence of Lewy bodies in the substantia nigra and locus coeruleus. "Bioinformatics analysis indicated that SNAP91 could serve as a primary biomarker for Parkinson's disease and AD." (PMID 35966780, 2022).
Anxiety (2 papers, 2025). Intense feelings of nervousness, tension, or panic often arise in response to interpersonal stresses. "Lactate-mediated lactylation of synaptosomal SNAP91 in the prefrontal cortex enhances synaptic plasticity, mitigating anxiety-like behaviors." (PMID 40331975, 2025). "In mouse models, exercise-induced lactylation of SNAP91 is crucial for preventing anxiety-like behavior after exposure to CRS." (PMID 41267100, 2025). "For instance, the lactate-mediated lactylation of synaptosomal SNAP91 in the prefrontal cortex enhances synaptic plasticity, mitigating anxiety-like behaviors, while lactate–lactylation networks regulate immunity–metabolism crosstalk in cardiovascular diseases via mitochondrial modulation." (PMID 40331975, 2025).
esophageal cancer (2 papers, 2021). A primary or metastatic malignant neoplasm involving the esophagus. "Low expression of SNAP91 was associated with poor prognosis in patients with esophageal cancer." (PMID 34211824, 2021). "Quantitative real-time PCR revealed that SNAP91 was lowly expressed in human esophageal cancer tissues and cell lines." (PMID 34211824, 2021).
glioma (2 papers, 2016 to 2021). A benign or malignant brain and spinal cord tumor that arises from glial cells (astrocytes, oligodendrocytes, ependymal cells). "Expression of SH3GL2 and SNAP91 also inversely correlated with glioma grade." (PMID 27655637, 2016). "We determined that RRM2 and COL3A1 were up-regulated and directly correlated with glioma grade, while SH3GL2 and SNAP91 were down-regulated in GBM and inversely correlated with glioma grade." (PMID 27655637, 2016). "We determined that RRM2 and COL3A1 were increased and directly correlated with glioma grade, while SH3GL2 and SNAP91 were decreased in GBM and inversely correlated with glioma grade." (PMID 27655637, 2016). "Expression of down-regulated DEGs SH3GL2 and SNAP91, which were found to be >2-fold lower in GBM samples by microarray analysis, was lower in malignant gliomas compared to non-tumor tissue and lower grade gliomas." (PMID 27655637, 2016).
anxiety disorder (1 paper, 2025). A category of psychiatric disorders which are characterized by anxious feelings or fear often accompanied by physical symptoms associated with anxiety. "Additionally, lactate produced by anaerobic exercise can enhance the Kla modification of synaptosome-associated protein 91 (SNAP91) in neurons, modulating synaptic structure in the medial prefrontal cortex (mPFC) and promoting neuronal motility, thus alleviating anxiety disorder." (PMID 41285721, 2025).
breast carcinoma (1 paper, 2019). "Furthermore, we observed splicing changes of known PTBP1 targets, PKM233,35, RTN438, SNAP91, and PTBP239, when PTBP1i was introduced into breast cancer cells." (PMID 30962446, 2019).
type 2 diabetes (1 paper, 2025). "In type 2 diabetes, genes like ST18, SNAP91, and SLBP are more central in the network, showing their importance in dealing with ongoing metabolic stress." (PMID 40909129, 2025).
cancer (3 papers, 2020 to 2022). A tumor composed of atypical neoplastic, often pleomorphic cells that invade other tissues. "Furthermore, we found that the expression of miRNA-222-3p was negatively correlated with SNAP91 expression in 14 different cancers." (PMID 33356818, 2021).
tumor (2 papers, 2016 to 2021). "Our results show that SNAP91 is associated with the metastatic phenotype of PCa and may facilitate tumor metastasis in PCa, which needs verification in our continued studies." (PMID 33356818, 2021).
nervous system diseases (1 paper, 2021). "Previous studies mainly reported the relationship between SNAP91 and nervous system diseases." (PMID 33356818, 2021).
SNAP91 also shares sentences with these, for which no sentence is quoted: epilepsy (2 papers); neurodegenerative disease (2); autism spectrum disorder (1); central nervous system disorder (1); cognitive deficit (1); colorectal cancer (1); infection (1); lactic acidosis (1); malignant glioma (1); neuroblastoma (1); neurodevelopmental disorder (1); Parkinson (1); retinal disease (1).